FAT1 (FAT atypical cadherin 1)
Diseases named in the same sentence as FAT1 in open-access papers (continued):
Sharing a sentence is not in itself a finding about the gene and the disease.
tumor (continued). "The precise molecular mechanisms that contribute to tumor development in the context of FAT1 functional loss or PIK3CA overexpression are not fully understood." (PMID 31817001, 2019). "In this work we have investigated whether OMVs could be engineered with the D8-FAT1 domain and whether D8-FAT1-decorated OMVs could induce anti-tumor immune responses against FAT1-positive tumors." (PMID 30416985, 2018). "While for many tumors the opposite role of FAT1 as tumor suppressor and tumor promoter is at present difficult to reconcile, in the case of CRC there might be a mechanistic explanation." (PMID 30416985, 2018). "However, as already pointed out, in some tumors FAT1 is up-regulated, suggesting that its Wnt/β catenin-dependent tumor suppressive mechanism is counterbalanced by a still poorly characterized role as tumor-promoting factor." (PMID 30416985, 2018). "CDKN2A (9%), FAT1 (23%), SMAD4 (11%), and CASP8 (13%) mutations were only present in HPV-negative HNSCC cell lines, which was consistent with the HNSCC TCGA data, where each of these mutations occurred in only 1 HPV-positive HNSCC patient tumor." (PMID 29156801, 2017). "Moreover, in vivo studies using Fat-1 transgenic mice showed remarkable decrease of tumor growth and metastasis to EO771 cells to lung in DHA-rich environment." (PMID 27363023, 2016). "Importantly, we confirmed inhibitory effects of DHA on in vivo tumor growth and metastasis using Fat-1 transgenic mice which maintained high-levels of ω3-PUFAs including DHA in their tissue." (PMID 27363023, 2016). "After 14 days, the average tumor volume was decreased by 80% in Fat-1 compared with WT." (PMID 27363023, 2016). "Additionally, we found that the levels of CD31 which is endothelial marker, was markedly suppressed in tumor tissue derived from Fat-1 mice than WT mice." (PMID 27363023, 2016). "Downregulation of FAT1 might also contribute the loss of aggressiveness in T-ALL, because knockdown of FAT1 in tumor cells results in a drastic inhibition of cell migration and invasion." (PMID 25644173, 2015). "In addition, detailed analysis of the diverse processed protein isoforms of the candidate tumor suppressor Fat1 can also contribute to our understanding of cell biology and tumor behavior." (PMID 24625754, 2014). "Notably, our study found that patients with FAT1 mutations in the LAML-KR cohort had a higher tumor mutation burden (TMB) compared to non-mutant patients." (PMID 40242237, 2025). "The tumor lineage and aggressive potential was confirmed by extensive genetic testing revealing a high tumor mutational burden and pathogenic mutations in TERT, NRAS, and NF1, alongside alterations in PBRM1 and FAT1, which may contribute to the tumor's unique morphology." (PMID 40125165, 2025). "Moreover, a widespread multi-omics analysis in more than 32 cancer types from The Cancer Genome Atlas (TCGA) dataset identified a genomic signature of 11 genes, correlated with TMB, able to predict the response to immunotherapy, which included FAT1 and NOTCH2, both mutated in our patient’s tumor." (PMID 40248199, 2025). "Furthermore, FAT1 has been shown to regulate various canonical signaling pathways, including Hippo, WNT/β-catenin, TGF-β, and PI3K/AKT, all of which have been proven to be relevant to immune regulation, indirectly substantiating FAT1’s regulatory role in the tumor immune system." (PMID 40672387, 2025). "Phylogenetic reconstruction demonstrated that the tumour regions showing CN-dependent and CN-independent ASE were found on different branches, suggestive of parallel evolution, with convergence upon the loss of different alleles of FAT1 through different mechanisms." (PMID 37046093, 2023).
tumor (continued). "Thus, increased THP-1 monocyte migration toward conditioned media from siFAT1-transfected tumor cells corresponds to and may be attributed to decreased immunosuppressive cytokine (TGF-β1/TGF-β2) production by FAT1-depleted tumor cells." (PMID 35720420, 2022). "Whether FAT1 serves a tumor suppressor or promoter seems to be cancer type-specific." (PMID 35965328, 2022). "Taken together, these results demonstrated that FAT1 may act as a tumor suppressor in OSCC." (PMID 35646625, 2022). "While it may be too early to confer the role of transcription factor to FAT1 for upregulation of EMT and stemness genes, it would now be fascinating to study the impact of GPC3 (and other GPC isoforms) interaction on FAT1 signaling event that initiates at the cell membrane of tumor cells." (PMID 33878524, 2021). "The FAT1 mutation in NB63R4 was acquired during relapse, while the FAT1 mutation in NB67R5 was present at the subclonal level with a 2% variant allele fraction in the primary tumor but increasing in relapse (i.e., a 15% variant allele fraction), indicating clonal expansion." (PMID 33384420, 2020). "Finally, we show that targeting unrestrained YAP1 may represent an attractive precision therapeutic option for cancers harboring genomic alterations in the FAT1 tumor suppressor genes." (PMID 29985391, 2018). "However, FAT1 may also function as an oncogenic protein since FAT1 promotes tumor migration via induction of actin polymerization, leading to loss of membrane localization, which is correlated with more aggressive tumors." (PMID 29228735, 2017). "Focusing on the PVT1 chromosome interval representing circPVT1, we did not observe any difference between tumor samples with either FAT1 or CDKN2A mutations and those with an intact FAT1 or CDKN2A gene, which were both up-regulated in comparison to non-tumoral samples." (PMID 29262850, 2017). "More importantly, our in vivo Fat-1 transgenic mice model showed a striking reduction of primary tumor growth as well as metastasis to lung suggesting that ω3-PUFAs-rich tissues provided beneficial environment to prevent both tumor progression and metastasis through inhibition of NF-κB." (PMID 27363023, 2016). "Fat1 activates the Hippo signalling pathway by promoting nuclear translocation of YAP1, which reduces the sphere‐forming ability and expression of tumour initiation markers in NSCLC cells, suggesting that Fat1 can inhibit NSCLC tumour initiation." (PMID 40665579, 2025). "Overexpression of FAT1 in NSCLC cells reduced stem cell markers and inhibited spheroid formation, potentially reducing tumor formation by promoting the nucleoplasmic translocation of YAP1." (PMID 40672387, 2025). "Other potential limitations include assessing for pLoF in oncogenic candidates such as RET, ROS1, FGFR4, and MYC, while FAT1 and LEF1 reported to oscillate between oncogenic and tumour suppressive behaviour." (PMID 41038821, 2025). "Knockdown of FAT1 enhanced cancer stem cell (CSC) properties and decreased the percentage of apoptotic tumor cells." (PMID 39781458, 2025). "We subsequently detected the expression of FAT1 in clinical HNSCC samples and found that the expression of FAT1 was significantly lower in tumor tissues than in normal epithelial tissues." (PMID 39781458, 2025). "qRT-PCR revealed significant upregulation of CXCL10, CXCL11, ME1, MT1X, FAT1, OAS2, and MT2A in tumor tissues compared to normal tissues." (PMID 40574841, 2025). "By regulating the Hippo pathway, FAT1 influences various molecular signaling pathways such as WNT/β-catenin, TGF-β, PI3K/AKT, and others, thereby affecting tumor progression." (PMID 40672387, 2025).
tumor (continued). "Cell Adhesion and Migration: CD44, ITGB1, LAMB1, FAT1, PLAUR, and TGFBI are integral to cell–matrix interactions and extracellular matrix (ECM) remodeling, processes critical for tumor invasion and metastasis." (PMID 41303451, 2025). "To investigate the impact of FAT1 on the growth of HNSCC, we constructed a subcutaneous tumor model in nude mice." (PMID 39781458, 2025). "FAT atypical cadherin 1 (FAT1), a tumor suppressor through WNT/β-catenin, Hippo, and MAPK/ERK pathways, influences tumor progression and affects therapy response in various cancers." (PMID 38167455, 2024). "These combined approaches enabled the identification of six tumour suppressor driver genes—namely BAP1, CREBBP, FAT1, NCOA6, RAD21 and UBR5—as regulators of the DDR and maintenance of chromosomal stability in NSCLC." (PMID 39738653, 2024). "Conversely, treatment with inhibitors led to an increase in H3K27me3 levels in FAT1 knocked out cells, supporting the view that CAMK2 activation can inhibit EZH2 and PRC2 activity in tumor cells." (PMID 38600608, 2024). "For example, disrupting the binding of KK-LC-1 to FAT1 can lead to a reduction in ALDH1A1 transcription, which reduces ALDH + cell stemness and viability and ultimately leads to the inhibition of TNCB tumour growth." (PMID 38916835, 2024). "In cSCC models, it was found that FAT1 deletions promote tumor initiation and progression, and increase YAP1 expression, promoting a mesenchymal state within the tumor tissue." (PMID 39199674, 2024). "Here we report that the protocadherin FAT1 acts as a critical upstream regulator of endothelial YAP/TAZ which limits the activity of these transcriptional cofactors during developmental and tumor angiogenesis by promoting their degradation." (PMID 37031213, 2023). "FAT atypical cadherin 1 (FAT1) is a cadherin that interacts both with the Hippo pathway and β-catenin, and it is reported to act as a tumor suppressor gene." (PMID 37833875, 2023). "Particularly, FAT1 is a tumor-suppressor that dampens the activity of the YAP Hippo effector; FAT3 is a homologous protein to FAT1; FRY is another inhibitor of YAP, blocking its nuclear translocation." (PMID 36661697, 2023). "In addition to the suppression of tumor initiation, FAT1 may also suppress metastasis." (PMID 35965328, 2022). "Estimated common deletion regions (CDRs) were observed in many tumor suppressor genes, such as ATM, CDKN2A, FAT1, miR31HG, PTEN, and RB1, in the SNP array-based COSMIC datasets." (PMID 36531022, 2022). "We analyzed the mRNA expression of FAT1 along with TGF-β1 and TGF-β2 in a tumor dataset containing 49 fresh-frozen human GBM tissues collected at AIIMS, New Delhi." (PMID 35720420, 2022). "Studies conducted over the past 20 years have demonstrated that FAT1 regulates multiple signaling pathways, including Wnt/β-catenin, Hippo and MAPK/ ERK, to affect the proliferation, migration, and invasion of various tumor cells." (PMID 36517565, 2022). "In this study, we have investigated the functional role of FAT1 in the regulation of TGF-β expression and production in tumor cells." (PMID 35720420, 2022). "Cases with biallelic FAT1 inactivation showed a drastic reduction in PFS (2.4 months), compared to patients with FAT1wt tumours (10.1 months)." (PMID 33671468, 2021). "FAT1 deletion promotes the acquisition of pEMT status in mouse and human SCC, thereby increasing tumor stemness and metastasis." (PMID 34421348, 2021). "It is possible that the functional interaction between FAT1 and ATAD3A is one of the critical molecular mechanisms underpinning ATAD3A-induced tumor growth." (PMID 33113782, 2020). "For example, in the case of tumour metastasis, in the group of patients with higher expression levels of YRNA1, downregulation of the FAT1 gene was noticed." (PMID 32455790, 2020).
tumor (continued). "We identified SNVs in the cadherin repeat domains of FAT family genes, i.e., FAT1 and FAT4 in 21% samples, which are functionally characterized as tumor suppressor genes in multiple cancers including ESCC." (PMID 32974170, 2020). "FAT atypical cadherin 1 (FAT1) regulates cell-cell adhesion and extracellular matrix architecture, while acting as tumor suppressor or oncogene, context-dependently." (PMID 31783581, 2019). "This suggests that alteration in YAP/TAZ upstream regulators (i.e., FAT1 and PIK3CA in HNSCC) takes place during HNSCC tumor progression leading to the activation of these two co-transcriptional factors and their target genes." (PMID 31817001, 2019). "LOH at 4q28.1–35.2 was also frequent in SCs (50%); this region includes the loci of tumor suppressor FBXW7 (F-box and WD repeat domain containing 7) and FAT1 (FAT tumor suppressor homolog 1)." (PMID 26043110, 2015). "Together, these facts indicate that FAT1 is tumor suppressive or oncogenic in a context-dependent manner and that FAT4 is preferentially tumor suppressive." (PMID 23076869, 2012). "It is of interest to note that expression of the chondroitin sulfate proteoglycan, versican, which is generally thought to have a tumor-promoting effect, trended lower (p = 0.057) in the n-3 PUFA-enriched Fat-1 tissues." (PMID 21655218, 2011). "The increase in tumor growth in the absence of FAT1 and MIB2 was again accompanied by increased expression of YAP/TAZ target genes as well as of YAP/TAZ protein." (PMID 40478800, 2025). "In this study, it is demonstrated that knockout of mutant FAT1 in HNSCC cells attenuates CPT1A‐driven fatty acid oxidation (FAO) through downregulation of the transcription factor ASCL2, leading to marked suppression of tumor growth." (PMID 40407216, 2025). "Since we recently described that in endothelial cells the intracellular domain of FAT1 interacts with the E3-ligase MIB2 to control YAP/TAZ protein degradation, we tested whether this interaction also occurs in tumor cells." (PMID 40478800, 2025). "The increased tumor growth of Hela cells lacking FAT1 and MIB2 was accompanied by increased expression of YAP/TAZ target genes and increased levels of YAP/TAZ protein in the tumors." (PMID 40478800, 2025). "We found that the tumor spheroids following FAT1 knockdown were not significantly diminished in number although they presented as significantly smaller than the control shRNA cultures." (PMID 40083689, 2025). "We then suppressed expression of FAT1 or MIB2 using lentiviral transfer of shRNA directed against FAT1 or MIB2 in Hela cells and in the FAT1-expressing HNSCC CAL27 and analyzed the growth of tumor cells in vivo after subcutaneous injection." (PMID 40478800, 2025). "While we found in all tested tumor cells that YAP/TAZ protein levels were regulated by FAT1 in a MIB2-dependent manner, not all cells showed CAMK2-dependent nuclear translocation." (PMID 40478800, 2025). "Thus, also under in vivo conditions, was the ability of FAT1 to increase YAP/TAZ protein degradation and to function as a tumor suppressor dependent on MIB2." (PMID 40478800, 2025). "Moreover, recent pancancer studies by The Cancer Genome Atlas Research in 9125 tumor samples have revealed that Hippo pathway components are widely altered in human cancers, such as downregulation of NF2, FAT1, TAOK1-3, WW45, and LATS1/2." (PMID 37211598, 2023). "We assessed the correlation between immune infiltration and the expression of 25 genes (IGHA1 is not available, and FAT is named FAT1) in TCGA-BRCA patients (n = 1100) using Tumor Immune Estimation Resource (TIMER) 2.0." (PMID 37445737, 2023).
tumor (continued). "We found enhanced miR-663a levels in U87MG, HepG2, and HeLa cells upon FAT1 knockdown as compared to siControl cells, indicating a role of FAT1 in modulating miR-663a that might indirectly regulate TGF-β1 expression in tumor cells." (PMID 35720420, 2022). "This leads us to deduce that FAT1 probably employs both cell growth-promoting features of some cytokines (such as IL-6) and immunity-evading properties of others (such as TGF-β) to the advantage of the tumor." (PMID 35720420, 2022). "In a clinical study, targeted sequencing of tumour and patient-matched normal DNA samples, from FFPE or peripheral blood, on 348 patients treated with palbociclib, ribociclib, or abemaciclib correlated FAT1 alterations with reduced PFS." (PMID 33671468, 2021). "The non-sRCCs were predominantly higher risk tumours; only 14 of the 268 (5%) had Hippo pathway alterations, involving NF2 (6/268), FAT1 (3/268), LATS1 (2/268), LATS2 (3/268) and YAP1 (1/268)." (PMID 31959902, 2020). "We found that in the lines, as in primary tumours, inactivating mutations in CASP8 did not result in a reduction in CASP8 expression, whereas FAT1 mutation did correlate with reduced mRNA levels." (PMID 27693639, 2016). "Herein, we demonstrated the use of a novel tumor targeting antibody directed against colon expressed FAT1 (clone mAb198.3) used for intracellular negative gold nanoparticles delivery." (PMID 26373379, 2015). "However, we found that the addition of exogenous interferon to tumor cells did not affect the protein expression level of FAT1." (PMID 39781458, 2025). "In addition, the type I interferon pathway is intricately intertwined with immunity, yet our exploration did not extend to investigating the influence of FAT1 on tumor immunity." (PMID 39781458, 2025). "However, in all tumor cells studied by us, loss of MIB2-mediated YAP/TAZ degradation appeared to be a requirement for increased tumor progression in the absence of FAT1 function." (PMID 40478800, 2025). "In addition, overexpression of FAT1 reduces stem cell markers and inhibits spheroid formation in non-small cell lung cancer (NSCLC) cells, and FAT1 may reduce tumor initiation in NSCLCs by promoting nucleoplasmic translocation of YAP157." (PMID 37147285, 2023). "Also, FAT1 was upregulated in tumor samples from two independent tumor and non-tumor pair-wise data sources (GSE6631 with HNSCs and GSE37991 with OSCCs; P < 0.0001, P < 0.001) and another set with 167 OSCCs and 45 normal oral tissues (GSE30784; P < 0.0001)." (PMID 35646625, 2022). "Moreover, we observed the FAT1 expression presenting an elevated trend in progressing tumor stages but not significantly." (PMID 35646625, 2022). "Our first pan-cancer analysis of FAT1 demonstrated a statistical correlation between FAT1 expression and clinical prognosis, protein phosphorylation, MSI, TMB, TME, and immune cell infiltration, which helped comprehend the role of FAT1 in tumorigenesis from the perspective of clinical tumor samples." (PMID 36517565, 2022). "To further examine whether circFAT1 promoted tumor growth in vivo, we knocked down circFAT1, but not FAT1 in SCC23 via lentivirus‐based short‐hairpin RNA for circFAT1 (shCFAT1)." (PMID 34258151, 2021).